CAV1 (caveolin 1)
Diseases named in the same sentence as CAV1 in open-access papers (continued):
Sharing a sentence is not in itself a finding about the gene and the disease.
lung carcinoma (continued). "CAV1 is downregulated in some cancer types, including lung cancer, colon cancer, ovarian carcinomas, and sarcomas." (PMID 36147736, 2022). "For instance, integrin β1 and Caveolin-1(Cav-1), a cell membrane component protein at Caveolae, co-participate in cell motility, invasion, and chemoresistance in lung cancer as well as PC." (PMID 35884437, 2022). "Knockdown of caveolin-1 inhibited the invasion and migration of lung cancer cells and increased therapeutic sensitivity of lung cancer to cisplatin-induced apoptosis." (PMID 35586682, 2022). "Despite the fact that the role of caveolin-1 in cancer is debatable, lung cancer has been shown to overexpress caveolin-1." (PMID 36366309, 2022). "We were able to identify 24 lung cancer patients (Adenocarcinoma and Squamous Cell Carcinoma) with altered CAV-1 gene." (PMID 34762666, 2021). "Immunohistochemistry data demonstrated heterogeneous expression of CAV-1 gene in human lung cancer tissues, which was analogous to its enhanced expression in human lung cancer cell line model and mouse orthotopic xenograft lung cancer model." (PMID 34762666, 2021). "It was shown that caveolin 1 (CAV1) is strongly expressed in lung cancer and positively correlated with lung metastasis." (PMID 33435156, 2021). "In the present investigation caveolin-1 (CAV-1) has been observed to be highly expressed in radiation resistant A549 lung cancer cells." (PMID 34762666, 2021). "In the present investigation, we have identified and characterized caveolin-1 as promising biomarker of radio-resistance and tumor progression in lung cancer." (PMID 34762666, 2021). "To further investigate expression of caveolin-1 in human lung cancer tissues, we performed immunohistochemistry analysis (IHC) in human lung tumor samples." (PMID 34762666, 2021). "The TCGA lung cancer genomic data analysis of lung cancer patients has shown CAV-1 gene amplification in 16 lung cancer patients, and 5 had CAV-1 gene deletion, and 3 had missense mutation in CAV-1 gene." (PMID 34762666, 2021). "In recent times, it was proven that the ectopic expression of miR-1827 contributes to the induction of anoikis by targeting CAV1 in lung cancer." (PMID 33435156, 2021). "In the present study, we investigated the molecular basis of radio-resistance in lung cancer A549 cells by knocking down caveolin-1 gene employing CRISPR-Cas9 gene editing technology." (PMID 34762666, 2021). "Further, CAV1 can protect lung cancer cells from anoikis by preventing ubiquitin-mediated degradation of myeloid cell leukemia sequence 1 (MCL1), a member of the anti-apoptotic BCL-2 family." (PMID 33435156, 2021). "On the other hand, overexpression of Cav-1 generated significantly higher superoxide anion level in lung cancer H460 cells while caveolin-1 specific shRNA transfection resulted in decreased superoxide generation." (PMID 32824727, 2020). "In the previous context, it has been discussed that multiple endogenous and exogenous agents can modulate Cav-1 expression to regulate lung cancer progression." (PMID 31991790, 2020). "Cav‐1 methylation can be a powerful predictor in the stable stage of lung cancer, and a potential biomarker for taxane‐based chemotherapy in lung cancers." (PMID 32508059, 2020). "In the present study, we explored the potential involvement of CAV-1, a key signaling protein associated with cancer progression, regarding TL-induced cytotoxicity in A549 and NCI-H460 lung cancer cells." (PMID 32733649, 2020). "In this review, we have summarized the valuable research on Cav-1 and lung cancer in recent years and discussed the multifaceted roles of Cav-1 on lung cancer occurrence, development and therapy, hoping to provide new insights into lung cancer treatment." (PMID 31991790, 2020). "CAV1 downregulation promotes proliferation, while the overexpression induces apoptosis in lung cancer cell lines." (PMID 32458269, 2020).
lung carcinoma (continued). "Cav-1 is a gene characterized as related with cigarette smoke, oxidative stress, cisplatin sensitivity, as well as lung cancer development." (PMID 31901898, 2020). "Converse studies have also shown that Cav-1 can induce lung cancer cell apoptosis in both histological types." (PMID 31991790, 2020). "Because the precise mechanism(s) of the anti-lung cancer activities of TL are incompletely defined, we sought to determine if TL treatment of lung cancer cells affects both CAV-1 expression and overall cell viability." (PMID 32733649, 2020). "Next, we assessed mRNA/protein expression of SIRT-1, a major deacetylase believed to play a pro-tumorigenic role in lung cancer and shown to be required for CAV-1 expression." (PMID 32733649, 2020). "Some studies have demonstrated the links between Cav-1 and the angiogenesis that occurs in lung cancer." (PMID 31991790, 2020). "In contrast, syntenin, a scaffold protein that can interact with multiple membrane receptors, is able to prevent TβR-1 internalization and degradation by disassociating the TβR-1/Cav-1 complex, finally to facilitate lung cancer progression." (PMID 31991790, 2020). "Cav‐1 also regulates cellular senescence, for example, senescent lung fibroblasts, contributing to the progression of lung cancer." (PMID 32508059, 2020). "Only the expression of Cav-1 is significantly decreased in lung cancer population, and positively correlated with that of lnc-BMP1-1 (R=0.211, P < 0.001)." (PMID 31901898, 2020). "RAC1 signalling was shown previously to be a key mediator of cancer migration modulating F-actin organization in colorectal cancer, while CAV1 has been demonstrated to promote cancer growth and migration in lung cancer." (PMID 33050615, 2020). "Cav-1 expression is greatly reduced in lung cancer compared with the normal pulmonary tissue, and its expression in cancer tissues with different histological types and stages also shows variation." (PMID 31991790, 2020). "Typically, in a majority of NSCLC cell lines (H460 and A549), Cav-1 has oncogenic characteristics that facilitate lung cancer cell proliferation." (PMID 31991790, 2020). "CAV1 reportedly functions as a tumor suppressor in several models including colon, breast and lung cancer, as well as melanoma cells." (PMID 32825247, 2020). "The protein level of Cav-1 is positively correlated with nab-paclitaxel sensitivity of lung cancer patients because of its membrane protein characteristics favoring drug intake and transport." (PMID 31901898, 2020). "Such cases indicate that Cav-1 knockdown can inhibit lung cancer cell proliferation via negatively regulating the cell cycle, which suggests a probably positive correlation between Cav-1 and lung cancer cell proliferation." (PMID 31991790, 2020). "A similar result was reported that high expression of Cav-1 in BM was correlated with a poor survival rate in lung cancer patients." (PMID 31297035, 2019). "In the present study, Cav-1 expression was evaluated in relation to lung cancer histotypes, the presence of BM, and prognosis." (PMID 31297035, 2019). "Based on the IHC analysis of Cav-1 expression, Cav-1 expression was higher in BM than in primary lung cancer of the SQC type." (PMID 31297035, 2019). "Research has reported that CAV1 regulates lung cancer’s apoptosis via STAT3 pathway, which suggests that CAV1 mediate STAT3 pathway in NSCLC." (PMID 31296840, 2019). "The comparison of Cav-1 expression in 49 paired cases (Group 2: BM and primary lung cancer from the same patient) according to histology (SQC vs. non-SQC) revealed histotype-associated expression results." (PMID 31297035, 2019). "Transient Cav-1 knockdown in both lung cancer cell lines reduced the expression of EMT markers, including N-cadherin and fibronectin, at the protein and mRNA levels." (PMID 31297035, 2019). "Recently, Cav-1 expression of fibroblast or macrophage in stromal component has been investigated in primary or secondary lung cancer." (PMID 31297035, 2019).
lung carcinoma (continued). "In lung cancer, overexpression of Cav-1 in primary cancer cells was significantly related to poor prognosis in patients with various histotypes." (PMID 31297035, 2019). "In vitro assays revealed that Cav-1 knockdown inhibited the invasion and migration of lung cancer cells." (PMID 31297035, 2019). "Based on an investigation of Cav-1 expression in distinct lung cancer histology, Cav-1 expression was decreased in 95% of SCLC cell lines but maintained in 76% of NSCLC cell lines." (PMID 31297035, 2019). "Although the decrease of Mcl-1 and Bcl-2 was notified after treatment with avicequinone B at 1–4 μM, the significantly reduction of caveolin-1 and induction of anoikis were only observed in human lung cancer cells incubated with avicequinone B at 4 μM." (PMID 29631569, 2018). "In this study, anoikis sensitizing effect of avicequinone B in human lung cancer cells involved with the down-regulation of caveolin-1 together with the reduction of Mcl-1 and Bcl-2." (PMID 29631569, 2018). "Avicequinone B at 4 μM significantly reduced the level of caveolin-1 in lung cancer cells detached for 12 h." (PMID 29631569, 2018). "To check the possibility that neddylation determines stability of caveolin-1, we measured the cellular levels of caveolin-1 in prostate, glioblastoma, and lung carcinoma cells which had been treated with MLN4924." (PMID 29301501, 2018). "Caveolin-1 was previously shown to play a role in attenuating anoikis response in lung cancer cells by maintain the level of Mcl-1." (PMID 29631569, 2018). "Previously, caveolin-1 was shown to inhibit anoikis through the preservation of anti-apoptosis Mcl-1 protein in detached lung cancer cells." (PMID 29631569, 2018). "The downregulation of caveolin-1 expression can also inhibit STAT3 signaling pathways to block lung cancer cell metastasis." (PMID 30424755, 2018). "In three datasets (GSE19804, GSE27716 and GSE40275), we found that referring to those patients at early stage of lung cancer, the expression level of CAV1 in patients at late stage was relatively low (P=0.007, P=0.005, P=0.001, respectively)." (PMID 29190968, 2017). "In lung cancer patients, compared with the adjacent tissues or normal lung tissue, the expression of CAV1 was down-regulated in cancer tissues." (PMID 29190968, 2017). "In human lung cancer cells, CAV1 expression is up-regulated by PEA3/E1AF and down-regulated by Net/Elk-3." (PMID 29340103, 2017). "In two cell-lines that were derived from metastatic lesions of lung cancer, Cav-1 was expressed at high levels, and siRNA-mediated knock-down (KD) of Cav-1 expression arrested cellular proliferation." (PMID 29221162, 2017). "Refer to those patients at early stage of lung cancer, the expression level of CAV1 in patients at late stage of lung cancer was relatively low." (PMID 29190968, 2017). "As scaffolding proteins are involved in the spatiotemporal regulation of signaling pathways the present study evidences caveolin-1 and Akap12 (gravin) to be regulated in lung cancer." (PMID 29254206, 2017). "In vitro, highly-metastatic lung cancer H1650-M3 cells displayed electrotaxis in a voltage-dependent manner, which was controlled by Cav-1-mediated STAT3 activation." (PMID 29221162, 2017). "Meanwhile, lung cancer H460 cells transfected with CAV1-specific shRNAs exhibited decreased superoxide generation and decreased cisplatin susceptibility." (PMID 28546853, 2017). "In this study, we analyzed the effects of cordycepin on lung cancer cell apoptosis and studied the relationship between CAV1 and JNK." (PMID 28099944, 2017). "The role of CAV1 in cancer is oncogene or tumor suppressor gene hasn't been agreed yet, and the role of CAV1 in lung cancer has rarely been studied." (PMID 29190968, 2017). "We found that compared with paired normal adjacent tissue or normal lung tissue, lung cancer tissue showed a relatively low level of CAV1 mRNA (P<0.001, P<0.001, respectively)." (PMID 29190968, 2017).
lung carcinoma (continued). "Cav-1 controls proliferation of metastatic lung cancer cells by regulating STAT3 signaling, while STAT3 can promote directional cell migration by organizing the actin cytoskeleton." (PMID 29221162, 2017). "Foxo3a siRNA downregulated Bax protein and attenuated A549 apoptosis, indicating that the CAV1-mediated JNK/Foxo3a pathway induces the apoptosis of A549 lung cancer cells." (PMID 28099944, 2017). "In lung cancer, increased expression of Cav-1 was observed upon advanced progression of the disease." (PMID 29221162, 2017). "Matrix metalloproteinase activation has been described in large cell lung carcinoma, where elevated CAV1 expression correlates with advanced stages of lung cancer as well as increased MMP9/MMP2 expression and activity." (PMID 29340103, 2017). "Our results suggest that the post-translational modification site of CAV1 at lysine 176 influences the drug transport activity of P-glycoprotein and the drug sensitivity of lung cancer cells." (PMID 26843476, 2016). "Cav1 expression in primary lung carcinoma and matched brain metastasis exhibited a significant association (chi-square test p < 0.001)." (PMID 26315660, 2015). "Cav1 expression in brain metastasis from lung cancer is independently predictive of worse outcome and radioresistance." (PMID 26315660, 2015). "In a taxol-resistant (9-fold resistant to taxol) lung cancer cell line A549, Cav-1 expression increased 3.4-folds compared to the parental cell line." (PMID 26431273, 2015). "With regard to CSCs, it was found that nitric oxide administration promoted CSC-like phenotype via elevating Cav-1 expression in lung cancer cells." (PMID 26431273, 2015). "A positive correlation exists between the upregulation of Cav-1 and the clinical features of primary lung cancer." (PMID 25202343, 2014). "While we have established CAV1 methylation is a predictive biomarker for taxane based chemotherapy response in lung cancer, a possible prognostic value independent from treatment needs to be considered as well." (PMID 25222296, 2014). "Our previous study showed that Cav-1 mediated anoikis resistant as well as increased migration and invasion in lung cancer cells." (PMID 24967418, 2014). "Here, we demonstrate for the first time that overexpression of Cav-1 in human lung cancer H23 cells significantly increased the formation of lamellipodia, whereas the suppression of Cav-1 using shRNA transfection had the opposite effect." (PMID 24955034, 2014). "Cav-1 expression has been shown to relate to poor prognosis and reduced tumor-free periods in lung cancer patients." (PMID 24967418, 2014). "Lung cancer H23 cells were transfected with either a caveolin-1 (Cav-1) overexpression or shCav-1 plasmid and further subjected to cell migration assays and lamellipodia characterization." (PMID 24955034, 2014). "A549 cells exhibiting the highest level of Cav-1 showed the strongest anoikis resistant potential in comparison to that of H23, H292, and H460 lung cancer cells, suggesting the role of Cav-1 in attenuating anoikis process in these cells." (PMID 24967418, 2014). "Before CAV1 methylation can be firmly established as predictive marker for taxane sensitivity in lung cancer, three important questions need to be discussed." (PMID 25222296, 2014). "Human lung cancer cells, namely, H460, H23 and A549 cells, were analyzed for endogenous Cav-1 levels by a western blot analysis." (PMID 24955034, 2014). "Silencing of CAV1 expression in lung cancer cell lines(A549, EKVX)by shRNA led to alterations in taxane retention." (PMID 25222296, 2014). "Further, we provided the evidence demonstrating the roles of Cav-1 on anoikis resistance and cell migration in H23 and other lung cancer cells." (PMID 24967418, 2014). "Caveolin-1 expression in lung cancer was shown to be related to poor prognosis and metastasis capability." (PMID 24967418, 2014).
lung carcinoma (continued). "Although some evidence has suggested the role of Cav-1 in suppressing cancer, in lung cancer, Cav-1 potentiates cancer progression and aggressiveness." (PMID 24967418, 2014). "It has been reported that expression level of Cav-1 correlates with paclitaxel resistance in lung cancer cells." (PMID 23613870, 2013). "In summary, the present study has revealed a novel finding on the cancer-endothelium regulatory effect of Cav-1 in human lung carcinoma H460 cells." (PMID 23460862, 2013). "The down-regulation of Cav-1 in lung cancer cells was shown to be dependent on the cellular redox status." (PMID 23460862, 2013). "Lung cancer H460 cells cultured in ultralow attachment plates were analyzed for Cav-1 protein expression by western blotting at indicated time points." (PMID 23460862, 2013). "Together, the present study revealed the novel role of Cav-1 and underlying mechanism on tumor adhesion which explain and highlight an important role of Cav-1 on lung cancer cell metastasis." (PMID 23460862, 2013). "In our study, we used real-time PCR and Western blotting assays to detect the expression of cav-1 mRNA and protein in lung cancer tissues and matched TF tissues." (PMID 22200856, 2012). "For example, CAV1 expression is frequently lost in colon cancer, ovarian cancer, lung cancer and sarcoma." (PMID 22152020, 2011). "As an additional validation we performed chromatin immune precipitation on the GRE upstream of the caveolin-1 gene in a human lung carcinoma cell line." (PMID 20098621, 2010). "In support of the notion that caveolin-1 modulates passage through the G2/M checkpoint, the chemotherapeutic drug, taxol, was shown to induce caveolin-1 accumulation and G2/M arrest in A549 lung cancer cells before these cells commit to cell death." (PMID 18400052, 2008). "Similarly, in lung cancer, proteins like caveolin-1 (CAV-1) and IL-13 receptor α2 contribute to AR by modulating autophagy and ROS responses." (PMID 40664635, 2025). "In addition, Cav-1 can also act on lung cancer-related cells, altering tumor progression and patient prognosis by affecting autophagy processes." (PMID 41030451, 2025). "Silencing CAV1 gene in human lung carcinoma cells decreases activated pSTAT3, suggesting that high levels of cav 1 could increase pSTAT3 and thereby block the expression of miR-204, as described in renal cancer cells." (PMID 37928877, 2023). "Knocking out Caveolin-1 in the A549 lung cancer cell line ultimately increases the sensitivity of lung cancer to cisplatin-induced apoptosis therapy by inhibiting Parkin-related mitophagy and amplifying cisplatin-induced mitochondria-related apoptotic signaling." (PMID 37323582, 2023). "In human lung carcinoma cells, ROS prevent Cav‐1 ubiquitination and degeneration." (PMID 35992829, 2022). "CAV1 increased oxidative stress protection and DNA repair, and its expression was correlated with radioresistance in rhabdomyosarcoma, pancreatic cancer, and lung cancer." (PMID 36119466, 2022). "Another study targeted gene associated with lung cancer and found four key genes that may affect lung cancer prognosis: MTIF2, ACOX1, CAV1, and MRPL17." (PMID 35039759, 2022). "It has also been reported that radiotherapy could change the expression of Caveolin-1, which could further affect the radiation response of pancreatic cancer and lung cancer." (PMID 36199626, 2022). "Also, a recent study demonstrated that Cav‐1 is involved in anoikis resistance in human lung cancer cells through regulation of myeloid cell leukemia 1 (Mcl‐1) by interacting with Mcl‐1 and preventing it from degradation." (PMID 35992829, 2022). "Thus, the lung cancer genome and RNA seq data suggest that predominantly, there was significant amplification in CAV-1 gene in lung cancer patients." (PMID 34762666, 2021).